NLRP3 (NLR family pyrin domain containing 3)
Diseases named in the same sentence as NLRP3 in open-access papers (continued):
Sharing a sentence is not in itself a finding about the gene and the disease.
lymphopenia (5 papers, 2022 to 2025). Reduction in the number of lymphocytes. "Together with the clinical features of lymphopenia and myelopoiesis/neutrophilia in patients with COVID-1942,43, our data suggest that the Omicron spike protein induces the NLRP3 inflammasome and inflammaging signaling and dysregulated myelopoiesis." (PMID 40025168, 2025). "Furthermore, NLRP3 inflammasome activation drives cells into pyroptosis, a process leading to cell-death by mean of gasdermin D, which may be the prominent cause of lymphopenia, and high levels of inflammation." (PMID 35327634, 2022). "Dysbiosis, disruption of the intestinal barrier, and activation of pattern‐recognition receptors such as TLR4 can trigger downstream NF‐κB and NLRP3 inflammasome signaling, fostering chronic systemic inflammation, cytokine release, and a shift toward neutrophilia with relative lymphopenia." (PMID 41466721, 2025).
measles (5 papers, 2020 to 2023). A highly contagious viral infection caused by the measles virus. "Transcriptomic analysis of peripheral blood mononuclear cells (PBMCs) from children with measles shows upregulation of mRNAs for IL-1β, CIAS-1/NLRP3, tumor necrosis factor (TNF)α, CCL4/MIP-1β, CXCL2/GRO-β, CXCL8, and TNFAIP3/A20 consistent with NF-κB signaling and inflammasome priming." (PMID 36851476, 2023).
meningitis (5 papers, 2013 to 2025). A disorder characterized by acute inflammation of the meninges of the brain and/or spinal cord. "As NLRP3 is one of the major sensors of LM, it is plausible that NLRP3 inflammasome play a role in the pathology of LM-associated meningitis." (PMID 28337127, 2017). "NLRP3 has been shown to be an important factor in the pathology of meningitis In pneumococcal-induced meningitis, the production of interferon (IFN)-γ was dependent on the protein ASC, which is an adaptor protein for multiple inflammasomes." (PMID 34149363, 2021). "To confirm that the inflammasome components ASC and NLRP3 were expressed or knocked out in our meningitis mouse model, we examined mouse brain homogenates from WT mice infected with S. pneumoniae serotype 3." (PMID 23902681, 2013). "Most notably, a recent study showed that NLRP3 mediates brain damage in an experimental meningitis model using a serotype 2 S." (PMID 23902681, 2013). "Administration of the NLRP3 inflammasome inhibitor MCC950 to mice prior to infection inhibited pyroptosis and protected PGRN ‐/‐ mice and BV‐2 cell model from meningitis." (PMID 39887961, 2025). "The results of our study indicated that in the meningitis mouse model constructed using S. pneumoniae serotype III, the NLRP3 inflammasome, ASC and caspase‐1, IL‐1β and IL‐18 expression all were increased." (PMID 39887961, 2025). "We then investigated the role of inflammasome gene NLRP3 and adapter protein ASC in a murine model of meningitis using serotype 3 S." (PMID 23902681, 2013).
nephrocalcinosis (5 papers, 2019 to 2025). Nephrocalcinosis is a disorder that occurs when too much calcium is deposited in the kidneys. "Moreover, immunohistochemistry analysis revealed high expression levels of NLRP3, caspase-1, and IL-1β in nephrocalcinosis samples." (PMID 34512861, 2021). "In oxalate-induced nephrocalcinosis, NLRP3 and ASC deficient mice failed to develop nephrocalcinosis, suggesting the protective effects of NLRP3 and ASC deficiency." (PMID 32175320, 2020). "NLRP3 in renal fibroblasts promoted fibrosis by augmenting TGF-β and Smad signaling without generating IL-1β, and thus NLRP3 inhibition could dampen nephrocalcinosis." (PMID 31694192, 2019). "However, the use of IL-1β inhibitors could not achieve the protective effect, revealing that NLRP3 inflammasome might act on nephrocalcinosis through other non-canonical pathway, possibly involving macrophage polarization and fibrosis." (PMID 32175320, 2020).
ocular infection (5 papers, 2019 to 2025). "Ocular infection of NLRP3 deficient mice led to more-severe and earlier stromal keratitis lesions and had higher angiogenesis scores than did infected wild-type animals." (PMID 31367214, 2019). "In an ocular infection model of Herpes-Simplex Virus-1, it has been shown that loss of Nlrp3 is associated with increased levels of pro-inflammatory cytokines including IL-1β and TNF-α, increased infiltration of neutrophils, and enhanced Th1 and Th17 cell responses." (PMID 34690967, 2021). "Whether cGAS-STING axis contributes upstream of NLRP3 during HSV1 ocular infection still requires further exploration." (PMID 35464953, 2022). "Additionally, itaconate reduces inflammation during S. aureus ocular infection by modulating NRF2/HO1 signaling and suppressing the NLRP3 inflammasome." (PMID 40795378, 2025).
orchitis (5 papers, 2019 to 2024). Inflammation of one or both testes due to viral or bacterial infections. "Activation of the NLRP3 inflammasome in orchitis promotes the secretion and maturation of IL-1β and, thus, decreases male fertility." (PMID 36289651, 2022). "We find that CaSR promotes the secretion of proinflammatory factor IL-1β in the NLRP3 inflammatory corpuscle pathway in orchitis and that CaSR inhibitors reduce inflammatory damage to spermatogenic epithelial cells." (PMID 33193351, 2020). "Previous research shows that the activation of the NLRP3 inflammasome in orchitis promotes the secretion and maturation of IL-1β and, thus, decreases male fertility." (PMID 33193351, 2020). "Activation of NLRP3 promoted the development of uropathogenic Escherichia coli-induced orchitis." (PMID 35915511, 2022). "Macrophages and NLRP3 inflammasomes are involved in the onset and development of orchitis." (PMID 33193351, 2020). "Despite that NLRP3 and inflammation-related IL-1β are upregulated in UPEC-infected TM, whether CaSR induces NLRP3 inflammasome activity in the pathogenesis of orchitis is unclear." (PMID 33193351, 2020). "Overall, elevated CaSR levels in TM in testes with UPEC-induced orchitis may impair testosterone synthesis through the activation of the NLRP3 pathway and PK2 is an upstream regulatory protein of CaSR." (PMID 33193351, 2020). "Overall, we revealed that increased PK2 levels in TM in UPEC-induced orchitis may impair testosterone synthesis via the activation of the NLRP3 pathway." (PMID 31474981, 2019). "Su and co-workers developed a uropathogenic Escherichia coli (UPEC) rat orchitis model, through which they investigated the NLRP3 inflammatory pathway proteins in testicular macrophages, and in particular, the expression of CaSR (calcium-sensing receptor), responsible for the NLRP3 activation." (PMID 36289651, 2022). "Thus, we speculated that CaSR can activate NLRP3 inflammatory bodies in orchitis." (PMID 33193351, 2020). "However, clinical progress in the treatment of orchitis by targeting NLRP3 is lacking." (PMID 38177538, 2024).
ovarian tumors (5 papers, 2020 to 2025). "Our earlier work demonstrated that ovarian tumor generation in NSG mice led to elevated NLRP3 inflammasome levels in skeletal muscle, which were subsequently reduced with WFA treatment." (PMID 39996717, 2025). "Here, a high level of NLRP3 was found in DPP-resistant ovarian tumors, whereas NLRP3 silencing can suppress cell proliferation, invasion, and migration and promote apoptosis of SKOV3/DPP and A2780/DPP cells." (PMID 37304662, 2023). "But there is limited experimental information on expression of NLRP3 inflammasomes in human ovarian tumors." (PMID 31923221, 2020). "The Human Protein Atlas suggests human ovarian tumors express NLRP3, caspase-1, IL1β and IL18." (PMID 31923221, 2020). "The study objective was to determine if the NLRP3 inflammasome components (NLRP3, caspase-1), and the corresponding cytokine products, IL1β and IL18, were increased in ovarian tumors." (PMID 31923221, 2020).
Pain (5 papers, 2020 to 2024). An unpleasant sensory and emotional experience associated with actual or potential tissue damage, or described in terms of such damage. "Previous studies have proposed the protective and beneficial effects of A3AR agonists in chronic neuropathic pain via inhibition of NLRP3 associated pathway." (PMID 35775127, 2022). "This study examined the effect of endurance training on the expression of NLRP3, P38 MAPK, TNF-α, and IL-1β genes in the spinal cord of rats with diabetic neuropathic pain." (PMID 35655729, 2022).
Peri-Implantitis (5 papers, 2021 to 2026). An inflammatory process with loss of supporting bone in the tissues surrounding functioning DENTAL IMPLANTS. "A cross-sectional study showed that inflammasomes (AIM2, NLRP3), and their downstream effectors (interleukin-1β, caspase-1), are strongly associated with specific bacteria in peri-implantitis." (PMID 40851867, 2025). "In prosthodontic tooth replacement, titanium corrosion particles and dysbiotic biofilms surrounding dental implants induce lysosomal stress and trigger strong NLRP3 activation, contributing to peri-implantitis—a process mechanistically similar to inflammation associated with orthopedic implants." (PMID 41596738, 2026). "Although extensive research has explored peri-implantitis and its association with NLRP3 inflammasome activation, evidence remains limited regarding how other dental prostheses—such as over contoured crowns and rough denture surfaces—contribute to NLRP3-mediated inflammatory responses." (PMID 41596738, 2026). "There are few studies that have analyzed in vitro the activation of NLRP3 in macrophages in response to triggers of peri-implantitis, such as metal ions or particles." (PMID 40490723, 2025). "In fact, if we consider the network analysis, it can be suggested that in peri-implantitis, NLRP3 plays a more relevant role compared with AIM2." (PMID 38256037, 2024). "LPS from P. gingivalis, another peri-implantitis-related pathogen, increases the mRNA levels of NLRP3, ASC, and caspase-1 in BMSCs, thereby increasing IL-1β production." (PMID 34177950, 2021). "Candida spp., frequently found in peri-implantitis lesions, can induce activation of the NLRP3 inflammasome." (PMID 34177950, 2021). "Titanium ions activate the NLRP3 inflammasome by increasing the production of ROS in Jurkat T cells, leading to immune responses in peri-implantitis." (PMID 34177950, 2021). "Within this debate, the activation of NLRP3, specifically, may help in finding a biologically plausible explanation for the differences between periodontitis and peri-implantitis." (PMID 38256037, 2024). "Only a recent study by our group has demonstrated that both the inflammasomes AIM2 and NLRP3 are highly expressed in peri-implantitis lesions from human patients and correlate with other markers of inflammation, tissue destruction, and clinical variables such as PD." (PMID 38256037, 2024). "In peri-implantitis, LPS + Ti strongly activates NLRP3, but without AIM2 activation, IL-1β and pyroptosis remain lower than in WT cells." (PMID 40490723, 2025). "Thus, differences in health and disease might be not properly represented, particularly if the expression of upstream regulatory molecules, predominantly NLRP3 in peri-implantitis as shown, are not looked at." (PMID 38256037, 2024).
prediabetes (5 papers, 2023 to 2025). "Importantly, higher NLRP3 levels in a female group with prediabetes suggest a potential sex-specific association, adding complexity to the inflammatory landscape of T2D." (PMID 39171751, 2024). "A significant overactivation of the inflammasome was observed in the prediabetes control group compared to healthy control subjects, as indicated by the results obtained through NLRP3, caspase-1, and IL-1β protein concentrations." (PMID 40761804, 2025). "Thus, in this cross-sectional study, we aimed to investigate, for the first time, the serum levels of NLRP3 with pro-inflammatory and anti-inflammatory ILs (1A, 1β, 33 and 37) in Saudi adults with different levels of glycemia, prediabetes (PD) and T2DM, and to compare them to healthy controls (HC)." (PMID 37238986, 2023). "On the other hand, the gene expression of NLRP3, CASPASE-1, and IL-1β, as well as the serum IL-1β concentration, decreased significantly in the prediabetes exercise group after 6 months of combined Yijinjing and resistance training." (PMID 40761804, 2025). "In another study conducted in middle-aged overweight or obese men with prediabetes, they evaluated the effect of a low-volume HIIT training program with different levels of compression, with or without berberine supplementation, on the upregulation of NLRP3 and IL-1β non-coding RNA." (PMID 40761804, 2025).
pterygium (5 papers, 2018 to 2024). A wedge-shaped fibrovascular lesion arising from the bulbar conjunctiva and extending to the cornea. "Activation of the NLRP3/caspase-1 pathway may be a cause of angiogenesis andfibroblast proliferation, which could induce pterygium recurrence." (PMID 32490975, 2020). "However, limited information is available on the association between the NLRP3 inflammasome and pterygium development." (PMID 31827916, 2019). "However, few reports have focused on the association between the NLRP3 inflammasome and pterygium." (PMID 31827916, 2019). "A recent study has explored several potential targets to reduce pterygium recurrence, including NLRP3, TGF-β1, VEGF, IL-6, and IL-8." (PMID 39682531, 2024). "Based on the results, we considered the possibility that MMC suppresses the activation of the NLRP3/Caspase-1 pathway to weaken neovascularization and fibroblast proliferation in pterygium." (PMID 31827916, 2019). "Herein, in situ immunohistochemical assays detected visibly higher expression of NLRP3 in pterygium tissue from group II patients than in tissue from group I patients." (PMID 31827916, 2019). "Further results demonstrated that MMC injection can significantly inhibit the activation of the NLRP3/Caspase-1 pathway in pterygium tissues and thus decrease the expression of IL-1β and IL-18." (PMID 31827916, 2019). "The protein levels of these factors were highly expressed in pterygium samples compared with normal conjunctiva samples with statistical difference (NLRP3, caspase-1, and IL-1β: P<0.05)." (PMID 29724886, 2018). "Another 30 pterygium samples and 30 normal conjunctiva samples were detected for NLRP3, caspase-1, pro-IL-1β, and IL-1β protein level with Western blot analysis." (PMID 29724886, 2018). "The mRNA of these factors was highly expressed in pterygium samples with statistical difference (NLRP3: P<0.001; caspase-1: P<0.001; IL-1β: P<0.05; IL-18: P<0.01)." (PMID 29724886, 2018). "Thirty pterygium samples and thirty normal conjunctiva samples were collected and analyzed for NLRP3, caspase-1, IL-18, and IL-1β mRNA expression using qRT-PCR." (PMID 29724886, 2018). "More importantly, our findings reveal that MMC reduces the recurrence rate of pterygium by suppressing angiogenesis and fibroblast proliferation via inhibiting NLRP3/Caspase-1 pathway activation and the expression of inflammatory factors such as TGF-β1, VEGF, IL-6." (PMID 31827916, 2019). "Therefore, MMC injection can attenuate the activation of the NLRP3/Caspase-1 pathway, thus inhibiting fibroblast proliferation and vascular hyperplasia and reducing the rate of pterygium recurrence." (PMID 31827916, 2019). "The expression of nod-like receptor pyrins-3 (NLRP3), caspase-1, IL-18, and IL-1β was analyzed in 60 human pterygium tissues and 60 human conjunctival epithelium tissues using real-time quantitative polymerase chain reaction (qRT-PCR) and Western blot analysis." (PMID 29724886, 2018). "Taken together, these results suggest that MMC not only inhibits tumour proliferation but also suppresses the activation of NLRP3 pathways and decreases the expression of inflammatory factors to prevent fibroblast proliferation and angiogenesis, thereby reducing the recurrence rate of pterygium." (PMID 31827916, 2019). "Anyway, our study provides multiple potential targets, including NLRP3, TGF-β1, VEGF, IL-6, and IL-8, for reducing recurrence of pterygium." (PMID 31827916, 2019). "Activation of NLRP3 inhibits the activation of NLRP6 in normal conjunctival and pterygium tissues." (PMID 36993972, 2023). "In addition, studies have shown a negative correlation between the expression of NLRP3 and NLRP6 in normal conjunctiva and pterygium." (PMID 36993972, 2023).
pulmonary TB (5 papers, 2016 to 2025). "We previously reported the protective gain-of-function effect of a Single Nucleotide Variant (SNV) in the NLRP3 3'UTR region (rs10754558; found in about 30% of the world population) against the development of pulmonary TB." (PMID 33193317, 2020). "In conclusion, we found that polymorphisms in CARD8 (C10X) and NLRP3 (Q705K) leading to a more susceptible inflammasome were associated with EPTB and poor treatment outcome in patients with pulmonary TB, respectively." (PMID 30816317, 2019). "Virulent mycobacteria lead to the activation of NLRP3 inflammasome through recognition of the ESAT-6 protein, However, a later study suggested that NLRP3 inflammasome activation was dispensable for the control of pulmonary tuberculosis." (PMID 27043315, 2016). "It remains unknown how the P2X7R and NLRP3 inflammasomesinfluence the occurrence of TAK combined with pulmonary tuberculosis." (PMID 41209134, 2025). "Our aim was therefore to explore the association between established polymorphisms (NLRP3 (Q705K) and CARD8 (C10X)) and pulmonary TB (PTB) as well as extrapulmonary TB (EPTB) including treatment outcome in Ethiopia, a high endemic setting for TB and in particular EPTB." (PMID 30816317, 2019).
renal carcinoma (5 papers, 2019 to 2025). A carcinoma arising from the epithelium of the renal parenchyma or the renal pelvis. "Another indirect NLRP3 modulator is resveratrol that suppresses the expression of NLRP3 in renal cancer cells." (PMID 36932407, 2023). "As control we investigated on the NLRP3 expression and production of IL-1β and IL-18 by cardiac cells and renal cancer cells during exposure to sunitinib alone or combined to resveratrol." (PMID 34178667, 2021). "In renal cancer cells and cardiomyocytes polydatin reduces expression of pro-inflammatory cytokines and chemokines involved in myocardial damages and chemoresistance and down-regulates the signaling pathway of NLRP3 inflammasome, MyD88 and NF-κB." (PMID 34178667, 2021). "According to our results, we demonstrated that LXRα functions as an important oncogene and could modulate the metastasis of renal cancer cells by down-regulate the NLRP3 inflammasome." (PMID 30770793, 2019). "Thus, we hypothesized that canagliflozin might prevent renal cancer from progressing by regressing NLRP3/IL-6/STAT3 activity." (PMID 41068541, 2025). "The low level of NLRP3 in renal cancer suggests that NLRP3 may play a tumor suppressor role in RCC." (PMID 37424068, 2023).